CYP3A4 (cytochrome P450 family 3 subfamily A member 4)
Diseases named in the same sentence as CYP3A4 in open-access papers (continued):
Sharing a sentence is not in itself a finding about the gene and the disease.
delirium (3 papers, 2021 to 2025). A disorder characterized by confusion; inattentiveness; disorientation; illusions; hallucinations; agitation; and in some instances autonomic nervous system overactivity. "However, three of the 6 patients with MDR-1/ABCB1 or CYP3A4 gene mutation who received the first dose of ivermectin had mild (agitation) and two had severe side effects (agitation, delirium-like behavior, aggressive behavior and consciousness changes)." (PMID 33947344, 2021).
dementia (3 papers, 2018 to 2024). Loss of intellectual abilities interfering with an individual's social and occupational functions. "CYP2D6, CYP2C9, CYP2C19, and CYP3A4/5 geno-phenotypes are involved in the metabolism of over 90% of drugs currently used in patients with dementia, and only 20% of the population is an extensive metabolizer for this tetragenic cluster." (PMID 32357528, 2020).
fibrosis (3 papers, 2016 to 2024). the formation of excess fibrous connective tissue in an organ or tissue in a reparative or reactive process. "The MTs show basal and RIF-induced CYP3A4 activity and TGF-β1-treatment-induced fibrosis." (PMID 34575957, 2021).
Hepatitis (3 papers, 2018 to 2023). Inflammation of the liver. "Liver-protective effects of Fructus Schisandrae via the inhibitory effect of CYP-3A4 activity have been reported and may also ameliorate the side effects of hepatitis resulting from the use of anti-TB medication." (PMID 30497462, 2018). "Metamizole is not listed as a drug with DDI potential in the summary of product characteristics; however, the University of Liverpool hepatitis drug checker describes a possibility of decreased concentration of SOF/VEL, GLE/PIB or EBR/GZR due to induction of CYP3A4 by metamizole." (PMID 34073674, 2021).
migraine (3 papers, 2022 to 2025). "Since the patient was taking rimegepant for migraines, strong CYP3A4 inhibitors (itraconazole, posaconazole, and voriconazole) were avoided and isavuconazole, a moderate CYP3A4 inhibitor, was selected." (PMID 41473476, 2025). "Since CYP3A4 inhibitors usually inhibit P‐gp, characterizing the extent to which rimegepant interactions are attributable to CYP3A4 inhibition from those due to transporter inhibition will further facilitate the safe and appropriate use of rimegepant in individuals with migraine." (PMID 35304977, 2022).
Myalgia (3 papers, 2015 to 2023). "The pathophysiologic mechanisms hypothesized to play a role in the development of statin-induced myalgias include competition at the cytochrome P-450 (CYP3A4) enzyme, deficiency of mitochondrial enzyme CoQ decreased plasma clearance in older patients, and/or vitamin D deficiency." (PMID 26382747, 2015). "It is theorized that in vitamin D deficient states, CYP3A4 preferentially hydroxylates 25-OHD instead of metabolizing statins, leading to statin-induced toxicity which may result in myalgias." (PMID 26382747, 2015).
osteomalacia (3 papers, 2018 to 2020). Disorder caused by an interruption of the mineralization of organic bone matrix leading to bone softening, bone pain, and weakness. "CYP3A4 lacks the specificity for vitamin D metabolites shown by CYP24A1, but drugs like rifampin can increase its expression leading to osteomalacia." (PMID 32051922, 2020).
osteonecrosis (3 papers, 2016 to 2022). A none disease characterized by death of bone tissue due to a lack of blood supply. "CYP3A4 polymorphism has been associated with both Finasteride concentrations and osteonecrosis." (PMID 36157219, 2022). "Genetic polymorphisms in several genes including SERPINE1, VDR, CYP3A4, TYMS, PAI 1, and ACP 1 were documented to be associated with osteonecrosis." (PMID 30533396, 2018).
peripheral T-cell lymphoma (3 papers, 2019 to 2025). "Since CYP3A4 metabolizes more than 50% of drugs currently used in chemotherapy and its expression in peripheral T-cell lymphoma (PTCL) is associated with a shorter survival rate, we focused our experiments on this member of the CYP3A family." (PMID 31105885, 2019).
primary biliary cholangitis (3 papers, 2016 to 2023). Primary biliary cholangitis (PBC) is a chronic and slowly progressive cholestatic liver disease of autoimmune etiology characterized by injury of the intrahepatic bile ducts that may eventually lead to liver failure. "This change could be specific to PSC, as the cholestatic condition primary biliary cirrhosis (PBC) is associated with substantially increased CYP3A4 protein levels." (PMID 28008998, 2016).
prostate tumors (3 papers, 2014 to 2025). "In fact, decreased expression of CYP3A4 has been found in prostatic tissues from PCa patients compared to 93% for benign epithelium, and only 75% of prostate tumors expressed CYP3A4." (PMID 24924803, 2014). "CYP3A4 and CYP2B6 are also inhibited by bergamottin but are not expressed in normal and prostate tumor cells." (PMID 34570813, 2021).
psychosis (3 papers, 2022 to 2025). "In the psychosis-diagnosis-only sample, there was evidence that CYP3A4 reduced metabolism was associated with lower quality of life scores." (PMID 40573287, 2025). "The incidence of psychosis, seizures and nephrotoxicity in CC individuals at CYP3A4*22 rs35599367 was significantly less than CT and TT recipients." (PMID 36246675, 2022). "The study only explored one route of psychosis drug metabolism using CYP2D6, and despite it playing a major role in metabolism, other cytochrome P450 enzymes, such as CYP1A2, CYP2C9/19 or CYP3A4/5 offer alternate metabolism routes for psychosis drugs." (PMID 38494658, 2024).
sarcoma (3 papers, 2015 to 2023). A usually aggressive malignant neoplasm of the soft tissue or bone. "Therefore, CYP3A4 is not a major contributor to resistance to taxanes in sarcoma spheroid models." (PMID 37958656, 2023).
serotonin syndrome (3 papers, 2020 to 2025). Serotoninergic syndrome is characterized by an excess of serotonin in the central nervous system, associated with the use of various agents, including selective serotonin reuptake inhibitors (SSRIs). "In fact, ginseng toxicity mainly comes from drug interactions with cytochromes P450 (CYPs) CYP3A4 and CYP2D6 inhibitors and serotoninergic drugs, intensifying sedative effects or inducing cognitive disorders or a serotonin syndrome." (PMID 33066617, 2020). "Although it is not commonly associated with serotonin syndrome, its metabolism via CYP2D6 and CYP3A4 suggests a possible interaction with DXM, particularly in poor metabolizers of CYP2D6." (PMID 40673125, 2025). "While aripiprazole alone is not a common cause of serotonin syndrome, its metabolism via CYP2D6 and CYP3A4 suggests a possible interaction with residual DXM metabolites, which may have delayed serotonin clearance and increased the risk of toxicity." (PMID 40673125, 2025).
tuberous sclerosis (3 papers, 2021 to 2025). Hereditary disease characterized by seizures, intellectual disability, developmental delay, and skin and ocular lesions. "In a retrospective PGx study in children with Tuberous Sclerosis Complex (TSC), the CYP3A4 polymorphism (CYP3A4*22) was shown to have an important role in the efficacy and manifestation of side effects following Everolimus treatment in these patients." (PMID 41009999, 2025). "For example, CYP3A4 and CYP3A5 polymorphism did not significantly affect sirolimus clearance rates in children with tuberous sclerosis complex." (PMID 34819851, 2021).
Tumor Lysis Syndrome (3 papers, 2021 to 2025). a group of metabolic abnormalities that can occur as a complication during the treatment of cancer, most commonly after the treatment of lymphomas and leukemias. "During the venetoclax ramp-up period, DDIs with strong CYP3A4 and P-gp inhibitors can result in life-threatening complications by significantly increasing the risk of tumor lysis syndrome (TLS) and severe myelosuppression (e.g., neutropenia, thrombocytopenia, or anemia)." (PMID 39830358, 2024).
Venous thrombosis (3 papers, 2021 to 2022). Formation of a blood clot (thrombus) inside a vein, causing the obstruction of blood flow. "However, the analysis of venous thrombosis among patients treated with apixaban and inducers of CYP3A4 and/or P-gp, which was the largest group of patients analyzed for this endpoint, indicates an increased risk for thromboembolism that needs further exploration." (PMID 33029651, 2021).
Ventricular arrhythmia (3 papers, 2017 to 2023). "Because domperidone, which is a peripheral D2 and D3 receptor antagonist is associated with ventricular arrhythmia, concomitant use of drugs that prolong the QTc interval, and potent CYP3A4 inhibitors should be avoided." (PMID 28651565, 2017).
vitamin D-dependent rickets type 3 (3 papers, 2023 to 2024). "A recurrent gain-of-function missense mutation (p.I301T) in the gene encoding CYP3A4 has been identified as a cause of excessive inactivation of vitamin D metabolites that causes vitamin D-dependent rickets type 3 (VDDR3)." (PMID 38179381, 2023).
acute pancreatitis (2 papers, 2017 to 2024). An acute inflammatory process that leads to necrosis of the pancreatic parenchyma. "The degree to which statins inhibit CYP3A4 and the degree of their lipophilicity may be correlated to their risk of causing acute pancreatitis." (PMID 38318563, 2024). "Another commonly suggested mechanism of statin-induced acute pancreatitis is the interaction of multiple drugs metabolized by CYP3A4." (PMID 38318563, 2024).
acute porphyria (2 papers, 2024). "Diclofenac and fluoxetine, CYP3A4 inhibitors, are associated with acute porphyrias." (PMID 39188285, 2024).
adenoma (2 papers, 2005 to 2023). A neoplasm arising from the epithelium. "In contrast, CYP3A4 protein levels of patients with adenoma with undetectable mRNA expression of CYP3A4 were significantly higher when compared to those with detectable mRNA expression." (PMID 16281975, 2005). "In contrast, in normal tissue of patients with adenomas protein levels of CYP3A4 and CYP3A5 were contrary to mRNA expression pattern." (PMID 16281975, 2005). "CYP3A4 protein concentration was ~69% lower in colon mucosa of patients with adenoma in comparison to disease-free controls." (PMID 16281975, 2005). "Similar results were found when comparing protein levels of CYP3A4 and CYP3A5 between patients with adenoma and disease-free controls." (PMID 16281975, 2005). "Expression of CYP2C, CYP2E1, CYP3A4, and CYP3A5 in colon mucosa of normal and adenomatous colonic tissue of patients with adenoma and disease-free controls was determined by RT-PCR." (PMID 16281975, 2005). "When comparing the relative mRNA concentration of CYP2C, CP2E1, CYP3A4, and CYP3A5 between adenomatous tissue and normal tissue of patients with adenoma, significant differences were only found for the expression of CYP3A5." (PMID 16281975, 2005). "At the level of protein, CYP2C8, CYP3A4, and CYP3A5 protein concentration was found to be significantly lower in normal tissue of patients with adenoma than in colon mucosa of disease-free controls." (PMID 16281975, 2005). "Taken together, these data suggest that CYP expression not only varies extensively between individuals but that protein levels of some CYPs (e.g. CP2C8, CYP3A4, and CYP3A5) are considerably lower in normal tissue of patients with adenoma in comparison to those of disease-free controls." (PMID 16281975, 2005). "Conversely, inhibitors of CYP3A4 (e.g., diltiazem and fluoxetine) can prolong dexamethasone bioavailability, which can suppress ACTH production by adenomas that are sensitive to negative feedback and thus lead to false-negative results." (PMID 37560300, 2023). "However, in normal tissue of patients with adenomas, protein levels of CYP2C8, CYP3A4 and CYP3A5, but not that of CYP2E1, were significantly lower than in biopsies obtained from disease-free controls." (PMID 16281975, 2005).
alcohol abuse (2 papers, 2019 to 2023). The use of alcoholic beverages to excess, either on individual occasions ("binge drinking") or as a regular practice. "CYP3A4*1G genetic mutation is associated with alcohol abuse and malignant diseases, with the correlation coefficient 0.09 and 0.1 (P<0.05)." (PMID 38117809, 2023). "The genetic mutation of CYP3A4*1G is supposed to be associated with malignant disease through the mechanism related to genetic mutation and alcohol abuse." (PMID 38117809, 2023). "Our research showed that CYP3A4*1G genetic polymorphism is related to alcohol abuse." (PMID 38117809, 2023). "Secondly, CYP3A4 genetic mutation, which may be associated with alcohol abuse, was related to heart diseases and malignant diseases, a regular check-up for specific population of alcohol abuse is essential." (PMID 38117809, 2023). "Although our study has shown that CYP3A4 mutation is related to alcohol abuse, the mechanism is unclear, and the number of participants with drinking habits was limited, which may have potential bias." (PMID 38117809, 2023). "CYP3A isoenzymes are related to patients with alcohol use disorder by regulating haloperidol concentration.The effects of CYP3A4 rs4646437 on drug is the most studied." (PMID 31799230, 2019). "Participants with CYP3A4*1G mutation(GA+AA) had an increased adjusted odds ratio (AOR) of 2.56 (95% CI, 1.4–4.65; P = 0.00) for alcohol abuse when compared with participants without CYP3A4 mutation (GG)." (PMID 38117809, 2023). "The association between polymorphisms of CYP3A4 genotypes and alcohol abuse is not clear." (PMID 38117809, 2023).
allergic disease (2 papers, 2023). An immune response that occurs following re-exposure to an innocuous antigen, and that requires the presence of existing antibodies against that antigen. "For instance, terfenadine, a drug used to treat allergy symptoms, may cause serious side effects including delayed cardiac repolarization and ventricular tachycardia due to the accumulation of terfenadine in the body when CYP3A4 activity was inhibited." (PMID 37047744, 2023).
bladder cancer (2 papers, 2015 to 2023). "The POR A503V variant-mediated decrease in metabolic CYP3A4 activation would generate decreased 2’-hydroxylated NNN and possibly reduce bladder cancer risk." (PMID 26123203, 2015).
Cerebral ischemia (2 papers, 2018 to 2025). Restriction of arterial blood supply to the brain associated with insufficient oxygenation to support the metabolic requirements of the tissue. "Their findings revealed that lamprophyllin could protect against cerebral ischemia–reperfusion injury by regulating intestinal microbiota, inhibiting TLR4/MyD88/NF-κB inflammatory pathways in the brain, and regulating intestinal CYP3A4 expression." (PMID 40308697, 2025).
Cholestatic liver disease (2 papers, 2019 to 2021). "Activation of PPARα had a beneficial effect on cholestatic liver diseases, and was mainly involved in the inhibition of CYP7A1 and upregulation of CYP3A4, UGT1A, and SULT2A1, and induction of MDR2 to increase biliary phospholipids secretion." (PMID 30774596, 2019).
chronic lymphocytic leukemia (2 papers, 2021 to 2024). "Acalabrutinib (ACP) is a first-line treatment for chronic lymphocytic leukemia but suffers from poor and variable oral bioavailability due to its pH-dependent solubility, CYP3A4 metabolism, and P-gp efflux." (PMID 39739083, 2024). "This is true for the oral chemotherapeutic ibrutinib, used to treat chronic lymphocytic leukemia (CLL), which makes roughly equal contributions to hepatic and intestinal CYP3A4 metabolism." (PMID 34067565, 2021).
colorectal adenocarcinoma (2 papers, 2016 to 2021). The most common type of colorectal carcinoma. "HT-29 colorectal adenocarcinoma cells also showed higher expression of CYP3A5 than that of CYP3A4." (PMID 27119350, 2016).
diarrhoea (2 papers, 2008 to 2024). "The mechanism by which the CYP3A4 status influences the occurrence of irinotecan-induced diarrhoea remains elusive, as the metabolites of irinotecan produced in this pathway do not display cytotoxic activity." (PMID 18797458, 2008).
erectile dysfunction (2 papers, 2021 to 2024). Persistent or recurrent inability to achieve or to maintain an erection during sexual activity. "Sildenafil citrate, a widely-used oral therapy for erectile dysfunction, is a cytochrome P3A4 (CYP3A4) enzyme substrate." (PMID 34199328, 2021).
Galactorrhea (2 papers, 2022 to 2023). Spontaneous flow of milk from the breast, unassociated with childbirth or nursing. "The drug metabolism process contributes to the mechanism by which omeprazole induces galactorrhea by inhibiting CYP3A4, leading to decreased metabolism of estrogen and thereby increasing serum estrogen levels." (PMID 35339194, 2022).
graft versus host disease (2 papers, 2022 to 2023). An immune system disorder that occurs after allogeneic hematopoietic stem cell transplant and is a reaction of donor immune cells against host tissues. "All patients received a co-administration of drugs metabolized through CYP3A4, cyclosporine, for graft versus host disease prophylaxis." (PMID 35337172, 2022).
Gynecomastia (2 papers, 2005 to 2023). Abnormal development of large mammary glands in males resulting in breast enlargement. "We hypothesize that the inhibition of CYP2D6 increased the concentration and side effects of venlafaxine (hyponatremia; additionally associated with the inhibition of CYP3A4), mianserin (restless legs syndrome), and paroxetine (gynecomastia/mastalgia)." (PMID 37829299, 2023). "In humans, prolonged ketoconazole therapy results in decreased clearance of 17β-estradiol, which may cause gynecomastia, presumably through inhibition of hepatic CYP3A4." (PMID 15701172, 2005).
head and neck cancer (2 papers, 2019 to 2020). A primary or metastatic malignant neoplasm affecting the head and neck. "From the head and neck cancer (HNC) gene expression dataset, the proposed method identified two additional genes (CYP3A4 and NOVA1) that are significantly enriched in linoleic acid metabolism, drug metabolism, steroid hormone biosynthesis and metabolic pathways." (PMID 31212673, 2019).
Hypercalcemia (2 papers, 2020 to 2025). An abnormally increased calcium concentration in the blood. "Another pharmaceutical therapeutic option is the enzymatic induction of CYP3A4 by rifampicin, which has been successfully used in patients with CYP24A1 mutations to diminish hypercalcemia and hypercalciuria." (PMID 41009532, 2025).
Hypocalcemia (2 papers, 2018). An abnormally decreased calcium concentration in the blood. "Since cabozantinib is metabolized by CYP3A4, hypocalcemia was considered as a potential contributing factor in reducing cabozantinib clearance in MTC patients." (PMID 29687244, 2018). "Her normal CYP3A4 activity, known to be responsible for mefloquine metabolism, and the normalization of QTc after correction of hypocalcemia, argues against any role for mefloquine in her arrest." (PMID 29581997, 2018). "Hypocalcemia may affect drug clearance indirectly via stimulation of active vitamin D metabolite 1,25 dihydroxyvitamin D3 (1,25(OH)2D3) synthesis, and subsequent induction of CYP3A4 by 1α,25(OH)2D3." (PMID 29687244, 2018).
influenza (2 papers, 2021 to 2025). An acute viral infection of the respiratory tract, occurring in isolated cases, in epidemics, or in pandemics; it is caused by serologically different strains of viruses (influenzaviruses) designated A, B, and C, has a 3-day incubation period, and usually lasts for 3 to 10 days. "In a previous case report, carbamazepine toxicity was found after influenza vaccination, suggesting that INF-γ may interfere with hepatic CYP3A4 enzymes, which are mainly responsible for metabolism of carbamazepine as well as multiple statins." (PMID 40276143, 2025).